RNU6-356P (RNA, U6 small nuclear 356, pseudogene)
Gene: Small nuclear RNA gene on chromosome 8 (41,032,892 to 41,032,998, forward strand). Ensembl gene ENSG00000206867.
Homologues: Orthologues: chimpanzee U6 (97% identical), rabbit U6 (89% identical), pig U6 (85% identical), pig U6 (84% identical). Paralogues in human: RNU6-338P (90% identical), RNU6-1124P (89% identical), RNU6-140P (89% identical), RNU6-25P (89% identical), RNU6-29P (89% identical), RNU6-33P (89% identical), RNU6-38P (89% identical), RNU6-393P (89% identical), RNU6-46P (89% identical), RNU6-664P (89% identical), RNU6-698P (89% identical), RNU6-1 (88% identical), and 1291 more.